FOXP1 (forkhead box P1)
Diseases named in the same sentence as FOXP1 in open-access papers (continued):
Sharing a sentence is not in itself a finding about the gene and the disease.
Anxiety (9 papers, 2017 to 2025). Intense feelings of nervousness, tension, or panic often arise in response to interpersonal stresses. "Since Nestin‐Cre (Foxp1‐/‐) mice show severely increased anxiety behavior and anxiety disorders are common in people with FOXP1 syndrome, we also performed several tests to investigate this further in Foxp1± animals." (PMID 40568906, 2025). "Most people with FOXP1 syndrome have autistic traits and behavioral problems such as hyperactivity, attention problems, impulsivity, aggression, anxiety, mood instability, obsessions, and compulsions." (PMID 40568906, 2025). "Moreover, loss of Foxp1, specifically in the pyramidal neurons of the neocortex and hippocampus, leads to intellectual disability, increased anxiety, communication impairments, and decreased sociability, indicating that the cerebral cortex may be the origin of ASD-like behaviors." (PMID 37691105, 2023). "Children and adults with FOXP1 syndrome present with behavioral symptoms that often include externalizing behaviors (i.e., hyperactivity or impulsivity), anxiety, and autistic traits." (PMID 34588003, 2021). "It revealed that Foxp1 mutant mice displayed significantly lower anxiety." (PMID 38280977, 2024). "The data demonstrated that Foxp1-cKO mice had increased locomotor activity and showed more anxiety." (PMID 37691105, 2023). "We have previously demonstrated that total lack of Foxp1 in the nervous system leads to severe behavioral abnormalities such as impaired social behavior and short-term memory, anxiety, and hyperactivity." (PMID 35052467, 2022). "The individual with the FOXP1 duplication presented with a similar phenotype, which included delays in reaching developmental milestones, borderline cognitive and adaptive functioning, visual-motor integration deficits, sub-threshold ASD symptoms, and clinically significant levels of anxiety." (PMID 29090079, 2017).
Obesity (9 papers, 2010 to 2025). Accumulation of substantial excess body fat. "FOXP1 represses brown/beige adipocyte differentiation and thermogenesis, with deficiency protecting against diet-induced obesity." (PMID 41012812, 2025). "Foxp1-deficient mice were reported to augment energy expenditure and be protected from diet-induced obesity, which is predicted to be slightly reduced in CR20-HFD males compared to the FED-HFD males." (PMID 38720938, 2023). "The Foxp1-deficient mice show an augmented energy expenditure and are protected from diet-induced obesity and insulin resistance." (PMID 31699980, 2019). "We submit that further investigation into mechanisms underlying Foxp1-mediated β3-AR regulation will cast new light upon the development of therapeutic strategies for obesity." (PMID 31699980, 2019). "The prediction analysis showed that FTOBD‐associated variants disturb binding sites of SP1 and SP2; obesity‐associated variants, on the other hand, disturb binding sites of FOXP1, which are transcription factors highly expressed during prenatal development stages of the brain." (PMID 31033179, 2019). "The additional findings of obesity and mild craniofacial anomalies (prominent forehead and frontal hair upsweep) in two patients might be part of the clinical spectrum associated with FOXP1 deletions." (PMID 20848658, 2010). "Over-expression of the FOXP1 in adipose cells affects adaptive thermogenesis and boosts diet-induced obesity." (PMID 36833449, 2023). "A recent study revealed the biological roles of Foxp1 in brown/beige adipocyte differentiation and thermogenesis, and overexpression of Foxp1 impairs adaptive thermogenesis and promotes diet-induced obesity in adipocytes." (PMID 37600712, 2023). "While FOXP1 was found to be a common interaction partner of PP1MB, SFTPC and TMEM67, an intriguing finding was that the BLM gene was the only common gene among PCa, diabetes mellitus, and obesity, interacting with both FOXP1 and TMPO." (PMID 38235353, 2023). "Consistently, overexpression of Foxp1 in adipocytes impairs adaptive thermogenesis and promotes diet-induced obesity." (PMID 31699980, 2019). "Our findings suggest that BAT activation and WAT browning in Foxp1-deficient mice results in marked improvement of glucose metabolism and protects mice from HFD-induced obesity (potentially as a result of elevated thermogenesis)." (PMID 31699980, 2019). "Taken together, our findings reveal Foxp1 as a master transcriptional repressor of brown/beige adipocyte differentiation and thermogenesis, and provide an important clue for its targeting and treatment of obesity." (PMID 31699980, 2019).
lung adenocarcinoma (8 papers, 2013 to 2024). A carcinoma that arises from the lung and is characterized by the presence of malignant glandular epithelial cells. "In lung adenocarcinoma, FOXP1 is also determined as a tumour suppresser gene by inhibiting chemokine signalling pathways." (PMID 38652109, 2024). "LINC01614 also promotes the carcinogenesis of lung adenocarcinoma by downregulating expression of microRNA-217 and upregulating expression of Forkhead Box Protein P1 (FOXP1)." (PMID 33362844, 2020).
pancreatic cancer (8 papers, 2020 to 2025). "In the present study, FOXP1 is highly upregulated in chemoresistant pancreatic cancer and plays a critical role in upregulating CSC properties and resistance to gemcitabine." (PMID 40169859, 2025). "Our study demonstrates that FOXP1 is highly upregulated in chemoresistant pancreatic cancer and is correlated with poor patient prognosis." (PMID 40169859, 2025). "In this study, we observed that FOXP1 is highly upregulated in gemcitabine-resistant (GR) pancreatic cancer and that higher FOXP1 expression leads to unfavorable patient outcomes." (PMID 40169859, 2025). "In the current study, we therefore aimed to investigate the transcriptional networks targeted by FoxP1 in skeletal muscle both in cancer-free conditions and in skeletal muscles undergoing wasting due to pancreatic cancer." (PMID 40349340, 2025). "Collectively, our findings suggest that FOXP1 is a potential target for combating CSC proliferation in chemoresistant pancreatic cancer." (PMID 40169859, 2025). "Together, our data reveal FOXP1 as a potent oncogene that promotes CSC growth in chemoresistant pancreatic cancer." (PMID 40169859, 2025). "Here, we found that the expression of the transcription factor Forkhead Box P1 (FOXP1) was elevated in chemoresistant pancreatic cancer and crucial for establishing CSC characteristics." (PMID 40169859, 2025). "Our findings indicated that FOXP1 drives chemoresistant pancreatic cancer to become more oncogenic, particularly through the enhancement of EMT and increased tumor proliferation." (PMID 40169859, 2025). "In conclusion, our findings show that FOXP1 plays an essential role in establishing chemoresistance in pancreatic cancer by enhancing CSC characteristics and upregulating ABCG2 expression." (PMID 40169859, 2025). "Analysis of overall survival and disease-specific survival in the TCGA-PAAD dataset revealed that patients with high FOXP1 expression had significantly lower survival rates, signifying that FOXP1 is a prognostic marker in pancreatic cancer." (PMID 40169859, 2025). "The analysis revealed the expression of OCT4 was increased in patients with high FOXP1 expression, signifying that FOXP1 plays a role in upregulating CSC-like characteristics in pancreatic cancer." (PMID 40169859, 2025). "Exosomes from the saliva of mice models bearing orthotopically implanted pancreatic cancer had higher mRNAs (Apbblip, Aspn, Incenp, Daf2, and Foxp1)." (PMID 39054529, 2024). "The expression level of FOXP1 protein was assayed in five pancreatic cancer cell lines, indicating a slight expression in PANC1 cells but an obvious increase in the other four cells." (PMID 36952469, 2023). "Our findings suggest that FOXP1 may serve as a prognostic biomarker in patients with chemoresistant pancreatic cancer." (PMID 40169859, 2025). "We observed a decrease in both OCR and ECAR in KD cells, indicating that FOXP1 may drive pro-glycolytic pathways in chemoresistant pancreatic cancer." (PMID 40169859, 2025). "Next, we assessed the FOXP1 expression in chemoresistant pancreatic cancer." (PMID 40169859, 2025). "We next evaluated the extent to which pancreatic cancer impacts circadian patterns of gene expression in skeletal muscle and whether this is mediated via FoxP1." (PMID 40349340, 2025). "We therefore designed experiments to determine whether pancreatic cancer alters circadian patterns of gene expression in skeletal muscle and whether this is mediated through FoxP1." (PMID 40349340, 2025). "In pancreatic cancer, FOXP1 has both tumor-suppressive and oncogenic roles." (PMID 40169859, 2025). "Thereby, FOXP1 has a potential ability to bind to the IRF1 promoter region in pancreatic cancer." (PMID 36952469, 2023). "Together, high-expressed FOXP1 efficiently inhibit the growth of pancreatic cancer in vivo." (PMID 36952469, 2023). "Together, FOXP1 positively inhibit the development and progression of pancreatic cancer cells." (PMID 36952469, 2023).
pancreatic cancer (continued). "Additionally, high expression of FOXP1 can markedly inhibit the growth of pancreatic cancer in vivo and in vitro, whereas low expression of FOXP1 effectively promoted the tumorigenesis." (PMID 36952469, 2023). "Therefore, we hypothesized that FOXP1 contributes to increased proliferation of chemoresistant pancreatic tumors." (PMID 40169859, 2025). "Notably, even in pancreatic cancer, a report reported that FOXP1 may act as a tumor suppressor." (PMID 40169859, 2025). "TCGA-PAAD analysis showed that FOXP1 and RRM1, which is a well-established marker upregulated in GR pancreatic cancer, have a significantly strong positive correlation." (PMID 40169859, 2025). "The depletion of FOXP1 led to decreased mRNA and protein expression of N-cadherin and vimentin and increased expression of E-cadherin, underscoring the role of FOXP1 in regulating EMT and metastasis in chemoresistant pancreatic cancer." (PMID 40169859, 2025). "FOXP1 mediated chemoresistance in pancreatic cancer by directly regulating ABCG2, further validating the crucial role FOXP1 plays in modulating chemoresistance in pancreatic cancer." (PMID 40169859, 2025). "However, the function and molecular mechanism of FOXP1 in pancreatic cancer (PC) remain unclear." (PMID 36952469, 2023). "Collectively, these findings demonstrate that, in response to pancreatic cancer, although the expression of clock genes remains rhythmic over 24 h, there is a bias toward the negative arm of the clock, which was mediated by FoxP1." (PMID 40349340, 2025). "Although FOX family genes and ABC transporters are correlated, there are no previous reports linking FOXP1 to ABC transporters in pancreatic cancer." (PMID 40169859, 2025). "However, the role of FOXP1 in pancreatic cancer, particularly in chemoresistance, has not been explored." (PMID 40169859, 2025). "However, neither the association between FOXP1 and chemoresistance nor the link to CSC proliferation in pancreatic cancer has been reported." (PMID 40169859, 2025). "Although FOXP1 regulates ABC transporters in other cancers, there have been no such reports for pancreatic cancer." (PMID 40169859, 2025). "We performed both luciferase reporter and ChIP assays to confirm that FOXP1 binds to the ABCG2 promoter, which has not been previously reported in pancreatic cancer." (PMID 40169859, 2025).
cervical cancer (7 papers, 2021 to 2025). A primary or metastatic malignant neoplasm involving the cervix. "HOXC8/NAT10/FOXP1 promotes progression of cervical cancer and formation of suppressive immune microenvironment by regulating glucose metabolism." (PMID 39640362, 2024). "In cervical cancer, NAT10/ac4C/FOXP1 induced the expression of GLUT4 and KHK, thereby promoting glycolytic metabolism and immune suppression." (PMID 39143228, 2025). "This study illustrates the oncogenic role of NAT10 in cervical cancer (CCa) and elucidates the mechanism by that the NAT10/ac4C/FOXP1 axis functions to accelerate glycolysis and promote infiltration of immunosuppressive Tregs into TME." (PMID 37818745, 2023). "Additionally, in cervical cancer, NAT10-mediated ac4C modification upregulates the expression of FOXP1, thereby reprogramming the glycolytic metabolic pathway to promote malignant progression of cervical cancer." (PMID 40303290, 2025). "NAT10/ac4C/FOXP1 axis was reported to facilitate immunosuppression and overexpression of FOXP1 was found to be positively related to the infiltration of activated CD4+ T cells and Tregs in cervical cancer, which supports our hypothesis." (PMID 38652109, 2024).
endometrial cancer (7 papers, 2014 to 2023). Primary or metastatic malignant neoplasm involving the endometrium (mucous membrane that lines the endometrial cavity). "They demonstrated that loss of ERα expression was a frequent event in cases with C-FOXP1 expression or loss of FOXP1 expression in endometrial carcinoma." (PMID 29848352, 2018). "Interestingly, Forkhead box P1 (FOXP1) is known to cause estrogen-dependent endometrial cancers through the KRAS pathway." (PMID 36498516, 2022).
follicular lymphoma (7 papers, 2014 to 2023). Follicular lymphoma is a form of non-Hodgkin lymphoma characterized by a proliferation of B cells whose nodular structure of follicular architecture is preserved. "NF-κB activation in malignant B cells can increase FOXP1 expression, but some results indicate that full-length FOXP1 may function as a NF-κB transcriptional repressor in follicular lymphoma." (PMID 27167345, 2016). "FOXP1 regulates the expression of multiple genes upon activation of BCR signaling, and overexpression of FOXP1 was correlated with a poor prognosis in CLL, DLBCL, and follicular lymphomas (FLs)." (PMID 28696359, 2017). "Further investigations showed that FOXP1-positive ABC-DLBCL, as well as follicular lymphoma and primary central nervous system lymphoma, preferentially express shorter FOXP1 isoforms, which in non-malignant conditions, may be induced by B-cell activation." (PMID 24416450, 2014).
leukemia (7 papers, 2014 to 2025). A malignant (clonal) hematologic disorder, involving hematopoietic stem cells and characterized by the presence of primitive or atypical myeloid or lymphoid cells in the bone marrow and the blood. "Next, we assessed the expression levels of FOXP1 in a panel of leukemia cell lines using RT-qPCR and found that FOXP1 expression levels were highest in the HL60, K562, Kasumi, and THP1 cell lines." (PMID 40672953, 2025). "Current evidence also supports a suppressor role for the transcription factor FOXP1 in the expression of both p21 and p27 in hematopoietic stem and leukemia cells." (PMID 30057418, 2018). "In addition, recent studies in leukemia cells have shown that PUM proteins can directly bind to the mRNA of the transcription factor FOXP1 to increase the expression level of FOXP1 protein, thereby increasing the proliferation of hematopoietic stem cells and myeloid leukemia cells." (PMID 35338151, 2022).
non-small cell lung carcinoma (7 papers, 2014 to 2020). A group of at least three distinct histological types of lung cancer, including non-small cell squamous cell carcinoma, adenocarcinoma, and large cell carcinoma. "High FOXP1 expression has previously been linked to metastasis and poor five-year OS in a cohort of 101 non-small cell lung cancer patients." (PMID 31745703, 2020). "Low FOXP1 expression has been reported to be associated with poor prognosis in non-small cell lung cancer, while NFAT1 has been reported to act as a tumor suppressor gene." (PMID 26465158, 2015). "Furthermore, decreased FOXP1 expression resulted in the best OS in patients with mucosa-associated lymphoid tissue (MALT) lymphomas (HR = 0.26, 95%CI: 0.11–0.59, p = 0.001), but the worst OS was observed in non-small cell lung cancer (NSCLC) patients (HR = 3.11, 95%CI: 1.87–5.17, p < 0.001)." (PMID 27457567, 2016).
colon cancer (6 papers, 2020 to 2025). "The expression of circFoxp1 was increased and Foxp1 was reduced in colon cancer tissues, which were associated with a poor overall survival rate of the patients with colon cancer." (PMID 32951006, 2020). "However, little is known about the molecular mechanism of Foxp1 loss in colon cancer." (PMID 32951006, 2020). "We revealed that circular RNA circFoxp1 derived from Foxp1 exons promoted the proliferation of colon cancer cells." (PMID 32951006, 2020). "Compared with normal colonic epithelial cells, the expression of circFoxp1 in colon cancer cells was significantly up-regulated, while the mRNA and protein expression of Foxp1 was significantly down-regulated, confirming their negative correlation." (PMID 32951006, 2020). "This study demonstrates that Foxp1 acts as a tumor suppressor in colon cancer and a new mechanism for its regulation." (PMID 32951006, 2020). "In order to study the role of circFoxp1 and Foxp1 in colon cancer, we used qPCR and IHC to detect the expression of circFoxp1 and Foxp1 in colon cancer tissues." (PMID 32951006, 2020). "In this study, we aim to investigate the role of circFoxp1 in colon cancer and the regulatory mechanism between circFoxp1 and Foxp1." (PMID 32951006, 2020). "We discovered a novel epigenetic pathway that circFoxp1 recruits DNMT1 to hyper-methylate the promoter Foxp1 in colon cancer cells." (PMID 32951006, 2020). "In this study, we found that the expression of circFoxp1 and Foxp1 in colon cancer tissues was negatively correlated, and circFoxp1 hypermethylated the promoter of Foxp1 by recruiting DNMT1, thereby inhibiting the expression of Foxp1, and ultimately promoting the colon cancer progress." (PMID 32951006, 2020). "We found that interfering circFoxp1 by siRNA in SW620 cells significantly inhibited cell viability, while knockdown Foxp1 expression partially restored SW620 cell viability, suggesting that circFoxp1 promotes colon cancer cell proliferation by inhibiting Foxp1." (PMID 32951006, 2020). "In addition, knockdown of circFoxp1 significantly sensitized colon cancer cells to Capecitabine in vitro and vivo through regulating Foxp1." (PMID 32951006, 2020). "In contrast, the expression of Foxp1 was significantly reduced in colon cancer tissues, and the expression in stage III–IV was significantly lower than that in stage I–II; and survival analysis also found that the higher Foxp1 expression, the higher the patient’s overall survival rate." (PMID 32951006, 2020). "We discovered a novel epigenetic pathway that circFoxp1 regulated Foxp1 in colon cancer cells." (PMID 32951006, 2020). "In this study, we found that interfering Foxp1 by siRNA reduced the expression of E2F1 and Rb, and promoted the expression of AR and β-catenin, suggesting that Foxp1 is a tumor suppressor gene in colon cancer." (PMID 32951006, 2020). "FOXP1 and NEDD4L are plausible tumor suppressor genes in colon cancer." (PMID 40753397, 2025). "In colon cancer tissues, the expression of circFOXP1 and FOXP1 was negatively correlated." (PMID 38745044, 2024). "Furthermore, correlation analysis found that there was a significant negative correlation between Foxp1 and circFoxp1 expression in colon cancer tissues (Pearson r = −0.496, p = 0.0053)." (PMID 32951006, 2020).